DNM1L (dynamin 1 like)
Diseases named in the same sentence as DNM1L in open-access papers (continued):
Sharing a sentence is not in itself a finding about the gene and the disease.
Cognitive impairment (6 papers, 2022 to 2025). Abnormal cognition is characterized by deficits in thinking, reasoning, or remembering. "DNM1L-related disorders are associated with neonatal or infantile-onset encephalopathy with varying severity degrees of refractory epilepsy, hypotonia and cognitive impairment dependent on the specific causative variant." (PMID 39063023, 2024). "Furthermore, AD patients with mild cognitive impairment and mild/moderate AD had higher transcriptional levels of several genes related to mitophagy, such as p62, PARKIN, dynamin 1-like, and beclin 1, compared to people without cognitive impairment." (PMID 35655270, 2022).
lung adenocarcinoma (6 papers, 2013 to 2025). A carcinoma that arises from the lung and is characterized by the presence of malignant glandular epithelial cells. "DNM1L was associated with poor survival in lung adenocarcinoma patients when co-expressing with PKP3, and nuclear expression of DNM1L was correlated with not only poor prognosis for lung adenocarcinoma but also drug resistance during hypoxia." (PMID 24369726, 2013). "In both invasive breast cancer and lung adenocarcinoma, DNA damage response pathways were enriched in the DNM1L mRNA high quartile, consistent with engagement of DNA damage." (PMID 35447090, 2022). "The results showed that inhibiting glycolytic serine synthesis remarkably suppressed the proliferation of DNM1L‐KO lung adenocarcinoma cell lines." (PMID 33152171, 2021). "We further used NCT503 to block PHGDH, the rate‐limiting enzyme of glycolytic serine synthesis, and evaluated the role of this adaptive response in the proliferation of DNM1L‐KO lung adenocarcinoma cell lines." (PMID 33152171, 2021). "Our results revealed enhanced ECAR in DNM1L‐KO lung adenocarcinoma cell lines, indicating upregulated glycolysis." (PMID 33152171, 2021). "To investigate the potential mechanisms, we first investigated the biological role of DRP1 in lung adenocarcinoma cell lines and generated DNM1L‐KO CL1‐0 and A549 cells." (PMID 33152171, 2021). "To evaluate the mechanisms underlying the decrease in mitochondrial respiration, we examined the mtDNA copy number and respiratory complex in DNM1L‐KO lung adenocarcinoma cell lines." (PMID 33152171, 2021). "Among them, the most significant gene was DNM1L, which concurred with high expression of PKP3 and DNM1L associated with poor survival in lung adenocarcinoma patients." (PMID 24369726, 2013). "Moreover, high DNM1L mRNA expression correlates with poorer survival in a cohort of lung adenocarcinoma." (PMID 35447090, 2022). "Additionally, we found increased protein expression of ATF4 and PHGDH, along with upregulated mRNA levels of PCK2, PHGDH, PSAT1, and PSPH, in DNM1L‐KO lung adenocarcinoma cell lines." (PMID 33152171, 2021). "Of these, a significant association between increased mutational count in DNM1L mRNA high quartile versus DNM1L mRNA low quartile was found in invasive breast carcinoma and lung adenocarcinoma (out of 22 studies), with the inverse relationship not observed in any cancer type (and data not shown)." (PMID 35447090, 2022). "Given that OXPHOS was suppressed in DNM1L‐KO lung adenocarcinoma cell lines, we next examined whether OXPHOS was required for the proliferation and invasion of lung adenocarcinoma cell lines." (PMID 33152171, 2021).
ovarian carcinoma (6 papers, 2014 to 2024). A malignant neoplasm originating from the surface ovarian epithelium. "In ovarian cancer DNM1L gene amplification has been associated with poor patient outcomes." (PMID 39191946, 2024). "DNM1L gene amplification has been reported to correlate with cell cycle gene expression and poor patient outcomes in chemoresistant and recurrent ovarian cancer cases." (PMID 39191946, 2024). "Interestingly, interrogating TCGA data, ovarian cancers displayed the highest gene amplification events for the Drp1 gene DNM1L, among all cancers represented, albeit this alteration only being present in 8% of the samples (data obtained via cBioPortal for Cancer Genomics)." (PMID 24858344, 2014).
Sepsis (6 papers, 2021 to 2025). Sepsis is defined as life-threatening organ dysfunction caused by a dysregulated host response to infection. "While levels of mitochondrial fusion-related genes Opa1 and Mfn2 were not different between groups, levels of mitochondrial fission-related genes, Fis1 and Dnm1l, were increased in Sepsis by 16% (p = 0.0197) and 42.1% (p = 0.0416), respectively." (PMID 41315622, 2025).
cardiomyopathy (5 papers, 2010 to 2025). A disease of the heart muscle or myocardium proper. "Specifically, Dnm1l is a mitochondrial fission protein and functions in mitochondrial fragmentation and cell death in response to ischemia of cardiomyocytes, while a dominant Dnm1l mutation causes abnormal cardiac morphology and aberrant energy production in cardiomyopathy." (PMID 39285385, 2024). "One possible explanation for the Dnm1l-mediated cardiomyopathy is cardiac energy deficiency." (PMID 20585624, 2010). "However, cardiomyopathy seems rarely present in DNM1L-related phenotypes, and only one recent report describes that cardiac involvement can be a clinically important feature of DNM1L-related disorders." (PMID 39063023, 2024).
colorectal cancer (5 papers, 2018 to 2025). A primary or metastatic malignant neoplasm that affects the colon or rectum. "Additionally, in colorectal cancer cells, DNM1L boosts susceptibility to ROS‐induced apoptosis via a akin mechanism, as demonstrated in a previous experiment." (PMID 39811936, 2025).
gastric cancer (5 papers, 2017 to 2024). A primary or metastatic malignant neoplasm involving the stomach. "We then utilized the cohort information from these microarrays to explore the relationship between DNM1L expression and gastric cancer prognosis." (PMID 39507763, 2024). "We aim to investigate the relationship between DNM1L and the prognosis of gastric cancer, as well as to explore the function and mechanism of DNM1L in gastric cancer (GC)." (PMID 39507763, 2024). "In this study, we analyzed the expression differences of DNM1L in gastric cancer tissues and paracancerous tissues using The Cancer Genome Atlas (TCGA) and the Gene Expression Omnibus (GEO) database." (PMID 39507763, 2024). "Furthermore, we conducted enrichment analysis to investigate the function and mechanisms of DNM1L in gastric cancer, and lastly, we performed immune cell infiltration analysis using the CIBERSORT algorithm." (PMID 39507763, 2024). "The results of this study indicate that DNM1L is upregulated in gastric cancer (GC) and positively correlates with the T-stage and poor prognosis of GC patients, and it plays an important role in tumor immune infiltration." (PMID 39507763, 2024). "These hub genes such as SRC (Proto-Oncogene C-Src), DNM1L (Dynamin 1-Like) and POLR1C (polymerase (RNA) I polypeptide C) are critical downstream effectors of CEACAM6 in gastric cancer progression." (PMID 29137373, 2017). "However, the function of DNM1L in gastric cancer has never been explored." (PMID 29137373, 2017).
glioma (5 papers, 2018 to 2024). A benign or malignant brain and spinal cord tumor that arises from glial cells (astrocytes, oligodendrocytes, ependymal cells). "In conclusion, targeted down-regulation of the DNM1L/DRP1-FIS1 axis in glioma can regulate mitophagy and impact the remodeling and OXPHOS function of MRC, ultimately inhibiting tumor occurrence and progression." (PMID 39350223, 2024). "In contrast, when glioma cells were subjected to OE-DNM1L treatment, these molecular expression changes exhibited an opposing trend, suggesting that DNM1L played a crucial role in modulating cellular autophagy and mitophagy." (PMID 39350223, 2024). "Expression levels of risk factors BRCA1, DNM1L, RCN1, HSPB1, RPN2, LRRK2 and SPP1 in high‐grade gliomas were greater than those in lower‐grade gliomas, while the protein expression levels of protective factor PDIA3 were exactly the opposite." (PMID 33611848, 2021). "Therefore, as the malignancy level of glioma cells increases, the elevated levels of DNM1L/DRP1 and FIS1 lead to heightened expression of PINK1/PARKIN, promoting mitochondrial fission and reshaping MRC through autophagy." (PMID 39350223, 2024). "Additionally, CYP2E1 regulates the level of ER stress and reactive oxygen species, PDIA3 is closely related to the anti‐tumour immunity of glioma, and DNM1L plays a regulatory role in the immune response of NKT cells to tumours." (PMID 33611848, 2021). "Our work, along with other studies reported in the literature, supports the notion that the inhibition of DNM1L/DRP1-FIS1 axis affects the remodeling of MRC and limits the aerobic respiration in glioma." (PMID 39350223, 2024). "The down-regulation of the DNM1L/DRP1-FIS1 axis significantly impaired mitophagy, thereby hindering the remodeling of MRC and inhibiting OXPHOS function in glioma, ultimately leading to the inhibition of its aggressive progression." (PMID 39350223, 2024). "Specifically, our study has demonstrated that targeted inhibition of the DNM1L/DRP1-FIS1 axis is essential for regulating mitochondrial division and inhibiting glioma progression." (PMID 39350223, 2024). "However, the levels of DNM1L/DRP1 and p-DNM1LSer616 were significantly elevated in grade 3 and grade 4 glioma compared to grade 1 glioma." (PMID 39350223, 2024). "Additionally, another DNM1L/DRP1 receptor MFF exerted opposite role in MRC, OXPHOS and glioma progression." (PMID 39350223, 2024).
Hyperglycemia (5 papers, 2018 to 2025). An increased concentration of glucose in the blood. "In silencing the expression of FIS1, the dynamin-1-like protein (drp1) through a small ARN of interference increased the production of the ROS induced by hyperglycemia, which suggests that the increase in mitochondrial fission can affect the endothelial function through the increase in ROS." (PMID 29808088, 2018).
Insulin resistance (5 papers, 2020 to 2025). Increased resistance towards insulin, that is, diminished effectiveness of insulin in reducing blood glucose levels. "Moreover, research has shown that the expression of the dynamin 1-like (DNM1L) protein, the human homolog of DRP1, in adipose tissue is associated with obesity and insulin resistance, indicating a potential role for mitochondrial fission in metabolic disorders." (PMID 39199152, 2024).
melanoma (5 papers, 2018 to 2021). A malignant, usually aggressive tumor composed of atypical, neoplastic melanocytes. "Specifically in melanoma, one study examining dynamin-1-like protein (DNM1L), which contributes to mitochondrial fission, found disrupted mitochondrial fission via the inhibition of DNM1L-induced melanoma cell death." (PMID 34831420, 2021).
viral infection (5 papers, 2021 to 2024). "During viral infection, phosphorylation of DNM1L (Ser616) is upregulated, promoting DNM1L recruitment to mitochondria and leading to mitochondrial fission, which initiates the PRKN-dependent mitophagy." (PMID 39273156, 2024). "Downregulation of dynamin-1-like protein and serpin H1-like genes in viruliferous T. palmi help in evading innate immune responses in T. palmi to favor the virus infection and multiplication in vector cells." (PMID 35369489, 2022).
cardiac hypertrophy (4 papers, 2019 to 2025). "Moreover, we found that only the re-expression Dnm1l and Mfn1 together could prevent the induction of cardiac hypertrophy by chronic mechanical overloading in a cell autonomous manner." (PMID 36276651, 2022). "Overexpression of Dnm1l and Mfn1 synergistically rescued YAP1-induced mitochondrial damages and cardiac hypertrophy." (PMID 36276651, 2022).
COVID-19 (4 papers, 2021 to 2024). A disease caused by infection with severe acute respiratory syndrome coronavirus 2. "IL-6, which is also expressed in both the acute and post-acute phase of COVID-19, induces expression of the mitochondrial fission proteins Dynamin-1-like protein and mitochondrial fission 1 protein in skeletal muscles cells and mice." (PMID 40603504, 2024). "Among the mitobiomarkers associated with the pulmonary version of COVID-19 are PTEN-induced kinase 1 (PINK1), dynamin-1-like protein (DNM1L) and mitofusin-2, which supports the relevance of oxidative stress and aberrations in mitochondrial motility (Chapter 9) in COVID-19 pathogenesis." (PMID 38974521, 2024). "Similarly, COVID-19 symptomatic cases also showed significantly lower expression levels of these genes compared to controls, together with a decrease in genes belonging to the mitochondrial respiratory chain subunits (NDUFA9, SDHA, COX4I1) and to mitochondrial dynamics (DNM1L, FIS1)." (PMID 34679654, 2021).
Infantile encephalopathy (4 papers, 2017 to 2024). Encephalopathy with onset in the infantile period. "Mutations in DNM1L (DRP1), which encode a key player of mitochondrial and peroxisomal fission, have been reported in patients with the variable phenotypic spectrum, ranging from non-syndromic optic atrophy to lethal infantile encephalopathy." (PMID 36212643, 2022).
lung carcinoma (4 papers, 2018 to 2021). "DNM1L (dynamin 1‐like protein) is essential for normal mitochondrial function and is upregulated in several cancer types including lung cancer." (PMID 32536039, 2020).
myocardial ischemia (4 papers, 2017 to 2025). A disorder of cardiac function caused by insufficient blood flow to the muscle tissue of the heart. "Herein, we have reported that heterozygous deficient Dnm1l mice exhibited a lower IRI degree when exposed to myocardial ischemia-reperfusion in vivo." (PMID 33765018, 2021). "The 3-month-old Dnm1l+/- and WT mice were subjected to 30-min myocardial ischemia followed by 24-hour reperfusion." (PMID 33765018, 2021). "After baseline characterization of the Dnm1l+/- mice heart, using echocardiography, electron microscopy, and oxygraphy, 3-month-old Dnm1l+/- and wild type (WT) mice were exposed to myocardial ischemia/reperfusion (I/R)." (PMID 33765018, 2021).
atherosclerosis (3 papers, 2023 to 2025). A disease characterized by the build-up of fatty material and calcium deposition in the arterial wall resulting in partial or complete occlusion of the arterial lumen. "Additionally, DNM1L is also potentially involved in PANoptosis in atherosclerosis." (PMID 40427707, 2025).
diabetic retinopathy (3 papers, 2022 to 2024). "Notably, such results were previously published in the case of diabetic retinopathy by Zhong and Kowluru, which might be related to the cytosolic location of Dnm1l, which is recruited during fission initiation." (PMID 37511204, 2023).
glaucoma (3 papers, 2023 to 2025). Increased pressure in the eyeball due to obstruction of the outflow of aqueous humor. "Research has indicated that, under conditions of pathologically high intraocular pressure, which is a hallmark of glaucoma, DNM1L induces mitochondrial dysfunction, leading to PANoptosis in retinal ganglion cells." (PMID 40427707, 2025).
osteosarcoma (3 papers, 2019 to 2025). A usually aggressive malignant bone-forming mesenchymal neoplasm, predominantly affecting adolescents and young adults. "Interestingly, high DNM1L expression was associated with a poor prognosis in patients with osteosarcoma but predicted better outcomes in patients with rhabdomyosarcoma, suggesting a possible sarcoma subtype–dependent role for mitochondrial fission in the therapeutic response." (PMID 39643272, 2025).
acute myeloid leukemia (2 papers, 2021). Acute myeloid leukemia (AML) is a group of neoplasms arising from precursor cells committed to the myeloid cell-line differentiation. "Misexpression of DNM1L and Mfn1/2 may underlie several human hematological malignancies including acute myeloid leukemia (AML), chronic myeloid leukemia (CML), chronic lymphocytic leukemia (CLL) and myelodysplastic syndromes." (PMID 34295888, 2021).
autism (2 papers, 2012 to 2025). Persistent deficits in social interaction and communication and interaction as well as a markedly restricted repertoire of activity and interest as well as repetitive patterns of behavior. "Identification of DNM1L pathogenic variants in the cohorts of patients affected by NDDs and autism prompted us to account for behavioral abnormalities during the review of clinical reports." (PMID 39859560, 2025). "The expression of DNAJC19, DNM1L, LRPPRC, SLC25A12, SLC25A14, SLC25A24 and TOMM20 were consistently reduced in at least two of the brain regions of autism patients compared to controls." (PMID 23116158, 2012). "The expression of DNAJC19, DNM1L, LRPPRC, SLC25A12, SLC25A14, SLC25A24 and TOMM20 were reduced in at least two of the brain regions of autism patients." (PMID 23116158, 2012). "The expression of DNM1L and LRPPRC were reduced in the ACG and MC of autism patients." (PMID 23116158, 2012).
gastric adenocarcinoma (2 papers, 2022 to 2024). "DNM1L has been recently reported as an important prognostic factor for gastric adenocarcinoma, involving invasion and apoptosis, which is partly in line with our findings in OS." (PMID 35504036, 2022).
kidney damage (2 papers, 2025). "Suppression of DNM1L in DKD can decrease tubular cell death and alleviate kidney damage, suggesting that it may have therapeutic relevance." (PMID 41318413, 2025).
prostate carcinoma (2 papers, 2022). A carcinoma that arises from epithelial cells of the prostate gland. "A recent study has shown that DNM1L upregulation by AR signaling in prostate cancer cells affects metabolism and tumorigenesis and its downregulation results in autophagy induction and proliferation inhibition." (PMID 35317831, 2022). "It seems that autophagy inhibition (for instance, by DNM1L upregulation), accelerates metabolic reprogramming in favor of prostate cancer progression." (PMID 35317831, 2022). "As dynamic structures, mitochondria shape, connectivity and subcellular distribution can be altered to enhance prostate cancer progression, a process modulated by DNM1L/DRP1 (dynamin 1 like)." (PMID 35317831, 2022).
status epilepticus (2 papers, 2019 to 2025). Status epilepticus is defined as a continuous seizure lasting more than 30 min, or two or more seizures without full recovery of consciousness between any of them. "Her subsequent clinical history, i.e., progressive neurological deterioration with seizures (status epilepticus and epilepsia partialis continua), is more clearly oriented towards a DNM1L pathogenic variant." (PMID 39859560, 2025).
cerebellar degeneration (1 paper, 2010). Degeneration of the cerebellum. "The fundamental importance of mitochondrial remodelling in mammalian pathophysiology has been underlined by in utero lethality and cerebellar degeneration in mice with homozygous mutations in Dnm1l itself, as well as Mfn1, Mfn2, or Opa1." (PMID 20585624, 2010).
cerebral palsy (1 paper, 2025). A group of disorders affecting the development of movement and posture, often accompanied by disturbances of sensation, perception, cognition, and behavior. "Moreover, DNM1L pathogenic variants have been identified in a cohort of patients with movement disorders and cerebral palsy." (PMID 39859560, 2025).
congestive heart failure (1 paper, 2010). Failure of the heart to pump a sufficient amount of blood to meet the needs of the body tissues, resulting in tissue congestion and edema. "Using this approach we describe a novel mouse model of DCM in which a mutation in the Dynamin-1-like gene (Dnm1l) leads to autosomal dominant DCM and congestive heart failure." (PMID 20585624, 2010).
Dystonia (1 paper, 2025). An abnormally increased muscular tone that causes fixed abnormal postures.